FGF21 (fibroblast growth factor 21)
Diseases named in the same sentence as FGF21 in open-access papers (continued):
Sharing a sentence is not in itself a finding about the gene and the disease.
dry eye (1 paper, 2023). "Our results also confirmed the role of FGF-21 in repairing ocular surface nerves on the scopolamine-induced dry eye model (data to be published in another article)." (PMID 37544647, 2023).
endometrioid endometrial carcinoma (1 paper, 2020). "FGF21 appears to be useful as a diagnostic as well as prognostic factor in patients with endometrioid endometrial carcinoma." (PMID 32570721, 2020). "Both FGF21 and leptin appear to be useful as a diagnostic, as well as showing a correlation with the degree of clinical and histopathological progress in patients with endometrioid endometrial carcinoma." (PMID 32570721, 2020).
enteropathy (1 paper, 2019). "FGF21 and environmental enteropathy markers may be especially useful for improving the targeted treatment and prevention of poor growth in children." (PMID 31093598, 2019).
epilepsy syndrome (1 paper, 2021). A syndrome that has a characteristic cluster of clinical features and/or lectroencephalographic (EEG) findings that reflect underlying epileptic activity. "However, this is only a hypothesis and a more comprehensive study with a larger sampling size should be used to investigate the association of FGF‐21 level with clinical outcomes in DS or other epilepsy syndromes." (PMID 34379890, 2021). "In addition, the neuroprotective mechanisms of FGF‐21 and the relationship with mitochondrial dysfunction can be further investigated for a possible therapeutic target for DS or other epilepsy syndromes." (PMID 34379890, 2021).
Erythema (1 paper, 2022). Redness of the skin, caused by hyperemia of the capillaries in the lower layers of the skin. "Visible histological changes, such as cutaneous erythema and swelling, were observed 24 h after the injection of C. acnes, with these alterations alleviated by FGF21 treatment." (PMID 35408949, 2022).
fat (1 paper, 2023). "This study showed a special FGF21-mediated fat conversion pattern in camels and provides a reference for developing a potential therapeutic method for fat metabolism disease." (PMID 36836789, 2023).
gastric cancer (1 paper, 2022). A primary or metastatic malignant neoplasm involving the stomach. "Increased FGF21 levels were observed in patients with different stages of gastric cancer, suggesting it is a suitable biomarker for early-stage gastric cancer." (PMID 36263162, 2022).
glioma (1 paper, 2024). A benign or malignant brain and spinal cord tumor that arises from glial cells (astrocytes, oligodendrocytes, ependymal cells). "However, in GBM, upregulation of FGF21 gene expression promotes glioma cell protrusion elongation." (PMID 39286013, 2024).
hematoma (1 paper, 2023). A hematoma is a collection of blood from a vascular structure into an extravascular space. "Based on the neurological examination and radiological parameters upon admission, patients in the upper quartiles of FGF21 had a greater NIHSS score and a larger hematoma volume but lower GCS score." (PMID 37214383, 2023).
hemorrhagic stroke (1 paper, 2024). A stroke caused by a bleed on the brain. "Thus, FGF21 has the potential to modulate neuroinflammation in hemorrhagic stroke." (PMID 38321473, 2024). "A clinical report determined serum FGF21 is the prognosis biomarker of ICH, suggesting its key role in hemorrhagic stroke." (PMID 38321473, 2024).
hyperinsulinemic hypoglycemia (1 paper, 2017). An inherited autosomal recessive syndrome characterized by the disorganized formation of new islets in the pancreas and congenital hyperinsulinism. "However, little is known about the changes of FGF21 levels in response to endogenous hyperinsulinemic hypoglycemia." (PMID 28225059, 2017).
Hyperkeratosis (1 paper, 2016). Hyperkeratosis is a histopathological term defining a thickened stratum corneum and may be present in many different skin conditions, with many possible overlaps. "More experimental studies need to be conducted to identify whether FGF21 is response to hyperkeratosis in AN and its related mechanism." (PMID 27190511, 2016).
hyperphosphatemia (1 paper, 2023). Abnormally high level of phosphate in the blood. "FGF-23 belongs to the same family of FGF-21 and acts as an endocrine nexus between hormones and mineral ions with the result of preventing hyperphosphatemia and hyper-vitaminosis." (PMID 37409233, 2023).
hypertensive nephropathy (1 paper, 2021). Kidney damage that results from chronically elevated blood pressure; complications include glomerular damage resulting in proteinuria and hematuria. "We discovered that the deficiency of FGF21 aggravated DOCA-salt-induced hypertensive nephropathy in mice." (PMID 34773993, 2021).
inflammatory bowel disease (1 paper, 2024). A spectrum of small and large bowel inflammatory diseases of unknown etiology. "The aim of the study was to assess correlations between serum FGF21 level and inflammatory markers as well as nutritional status indicators in patients with inflammatory bowel disease (IBD)." (PMID 38983722, 2024).
influenza infection (1 paper, 2025). "Our findings reveal an FGF21-regulated neuronal pathway that protects mice against influenza infection and suggest the potential utility of using FGF21 pharmacologically to improve outcomes after influenza infection." (PMID 40996795, 2025).
intracranial hemorrhage (1 paper, 2023). Bleeding within the SKULL, including hemorrhages in the brain and the three membranes of MENINGES. "We hypothesized that FGF21 may have protective effects after intracranial hemorrhage (ICH) and investigated possible underlying molecular mechanisms." (PMID 38049769, 2023).
Left ventricular diastolic dysfunction (1 paper, 2025). Abnormal function of the left ventricule during left ventricular relaxation and filling. "NLR and FGF21 are associated with echocardiographic parameters of left ventricular diastolic dysfunction prior to the fulfilment of LVDD diagnostic criteria." (PMID 41464745, 2025).
Lewis lung carcinoma (1 paper, 2023). "It is noteworthy that one study demonstrated that the anti-tumor effect of a KD was FGF-21-independent in a model of Lewis lung carcinoma." (PMID 37623854, 2023).
lipidosis (1 paper, 2023). "Changes in hepatic triglyceride content may be more pronounced in cats with hepatic pathology (e.g., lipidosis), and future studies are needed to determine if activation of the FGF21 pathway could be used to decrease hepatic triglyceride in more severely affected cats." (PMID 36756310, 2023).
lymph node metastasis (1 paper, 2025). "Furthermore, the PDAC patients with lymph node metastasis and vascular invasion have a higher proportion of low expression of FGF21." (PMID 41426308, 2025).
macrosomia (1 paper, 2021). "Assessment of FGF21 in early second trimester amniotic fluid of SGA, AGA, and LGA fetuses clearly points to an association of its levels with altered growth velocities, SGA, and macrosomia; it could thus play an important role as a prognostic factor for associated adverse perinatal outcomes." (PMID 34564397, 2021).
macular edema (1 paper, 2020). "Long-acting FGF21 may have therapeutic potential for preventing or treating macular edema in retinopathy as well as suppressing retinal neovascularization." (PMID 32054022, 2020). "Taken together, we propose that FGF21 could be a therapeutic target for preventing macular edema and proliferative retinopathies." (PMID 32054022, 2020).
major depressive episode (1 paper, 2022). "FGF21 was analyzed by ELISA in individuals with chronic, early-onset MDD (first major depressive episode before 30 years) compared to healthy control participants." (PMID 35017468, 2022).
mental disorder (1 paper, 2021). A disease that has its basis in the disruption of mental process. "However, the association between CSF FGF21 and impulsivity in the patients of mental disorders with impulsivity needs to be furtherly investigated." (PMID 34800969, 2021). "Further future research should seek to clarify whether CSF FGF21 could be a biomarker of impulsivity for impulsivity-related mental disorders." (PMID 34800969, 2021). "The current study demonstrated that CSF FGF21 may be an interesting and important biomarker used to evaluate the standard of impulsivity in the general population and to screen potential population of mental disorders related to impulsivity." (PMID 34800969, 2021).
Methylmalonic aciduria (1 paper, 2023). Increased concentration of methylmalonic acid in the urine. "Elevated Fgf21 in fed conditions is consistent with findings from another mouse model of methylmalonic aciduria (Mmut−/−;TgINS-MCK-Mmut) and methylmalonic aciduria patients and is positively predictive of muscle mitochondrial pathologies in a quantitative manner." (PMID 37369025, 2023).
muscle atrophy (1 paper, 2025). The loss of muscle tissue due to inactivity or disease. "Our findings reveal a novel role and heretofore unrecognized mechanism of FGF21 in skeletal muscle atrophy, suggesting that inhibiting muscular FGF21 could be a promising strategy for mitigating skeletal muscle atrophy." (PMID 40998017, 2025).
neuropathy (1 paper, 2022). A disorder affecting the nervous system that manifests with pain, tingling, numbness, and/or muscle weakness. "The physical activity mayincrease the level of FGF21 in T2DM patients with neuropathy." (PMID 39077619, 2022). "Wehypothesized that an increase in FGF21 level may induce lipolysis in adiposetissue, especially via activation of hormone sensitive lipase and adiposetriglyceride lipase, and enhance mitochondrial function as a result of physicaltraining T2DM subjects with neuropathy." (PMID 39077619, 2022).
obstructive sleep apnea (1 paper, 2025). "The second study described the correlation between the FGF-21 levels and obstructive sleep apnea." (PMID 41010737, 2025).
ophthalmoplegia (1 paper, 2017). Weakness or paralysis of at least one of the muscles controlling the movement of the eye. "However, we found patients with ophthalmoplegia to have higher FGF-21 concentrations." (PMID 28825656, 2017).
opioid dependence (1 paper, 2022). "Interestingly, morphine analgesia and tolerance development were not altered in FGF21-Tg mice, showing that FGF21 plays a role in opioid dependence but not in analgesia or tolerance." (PMID 36532632, 2022).
osteosarcoma (1 paper, 2016). A usually aggressive malignant bone-forming mesenchymal neoplasm, predominantly affecting adolescents and young adults. "Though both FGF21 and TZDs have been found to enhance adipogenesis in mesenchymal stem cells, their cooperative effects on the differentiation process in osteosarcoma cells have not been elucidated." (PMID 27528232, 2016).
ovarian carcinoma (1 paper, 2023). A malignant neoplasm originating from the surface ovarian epithelium. "Modulation of FGF21 levels by overexpression or siRNA silencing confirmed that FGF21 overexpression induces chemoresistance in ovarian cancer cells." (PMID 37438818, 2023). "Together these data suggest that additional studies on expression of FGF21 in ovarian cancer and its role in therapeutic response are warranted." (PMID 37438818, 2023). "Little is known about the role of FGF21 in ovarian cancer; however a recent report identified FGF21 as a highly significantly upregulated gene when comparing cisplatin-resistant human ovarian cancer cells (A2780CP) to the parental cell line (A2780)." (PMID 37438818, 2023).
ovarian failure (1 paper, 2024). "As 17β-estradiol treatment was associated with lower serum FGF21 concentrations in ovariectomized women, FGF21 resistance may be improved by hormone therapy in women with ovarian failure." (PMID 39354624, 2024).
pancreatic ductal adenocarcinoma (1 paper, 2025). An infiltrating adenocarcinoma that arises from the epithelial cells of the pancreas. "Although Fibroblast Growth Factor 21(FGF21) exhibits potent anti-inflammatory effects in pancreatic tissue, its endogenous levels are markedly decreased in pancreatic ductal adenocarcinoma specimens." (PMID 41426308, 2025).
pertussis (1 paper, 2024). A contagious bacterial respiratory infection caused by Bordetella pertussis. "Additionally, 3 inflammatory cytokines – IL-4, IL-18R1, and FGF-21 – show a causal relationship with pertussis." (PMID 39612418, 2024). "Three inflammatory cytokines were found to have a causal relationship with pertussis: IL-4 (OR = 0.3688, 95% CI = 0.16571–0.8208, P = .0145418), IL-18R1 (OR = 1.2757, 95% CI = 1.0499–1.5501, P = .0143), and FGF-21 (OR = 2.0747, 95% CI = 1.0669–4.0341, P = .03147)." (PMID 39612418, 2024). "This study also identified 3 inflammatory cytokines (IL-4, IL-18R1, and FGF-21) with causal relationships with pertussis, suggesting that these cytokines may play direct roles in the development of the disease." (PMID 39612418, 2024). "Although IL-4, IL-18R1, and FGF-21 were found to have direct causal relationships with pertussis, the 2-step MR analysis showed that inflammatory cytokines do not mediate the effect of immune cells on pertussis." (PMID 39612418, 2024).
primary biliary cholangitis (1 paper, 2025). Primary biliary cholangitis (PBC) is a chronic and slowly progressive cholestatic liver disease of autoimmune etiology characterized by injury of the intrahepatic bile ducts that may eventually lead to liver failure. "In a Phase 3 study in patients with primary biliary cholangitis, seladelpar treatment has been shown to increase serum Fgf21 while decreasing serum C4 and total bile acid levels." (PMID 40225907, 2025).
pseudotumor cerebri (1 paper, 2024). Idiopathic intracranial hypertension is a neurological disorder characterized by isolated increased intracranial pressure manifesting with recurrent and persistent headaches, nausea, vomiting, progressive and transient obstruction of the visual field, papilledema. "Enrichment analysis using DisGeNET revealed that genes related to Cystatin D expression in the brain were associated with childhood astrocytoma and pseudotumor cerebri, whereas genes related to FGF21 were linked to gout-related diseases." (PMID 38784036, 2024).
ptosis (1 paper, 2017). The drooping of the upper eyelid. "Also, patients who had ptosis and/or PEO also had median FGF-21 z-score that were comparable with those in patients without ocular myopathy (p = 108)." (PMID 28825656, 2017).
RASopathy (1 paper, 2024). Developmental syndromes caused by germline mutations (or in rare cases by somatic mosaicism) in genes that alter the Ras subfamily and mitogen-activated protein kinases that control signal transduction. "FGF-21: HCM is a common associated feature in RASopathies i.e., disorders caused by genetic variants in genes encoding for components in the RAS-MAPK cascade." (PMID 38667723, 2024). "Patients with RASopathy-associated HCM were excluded from our study and we still find an upregulation of FGF-21 with an OR for HCM of 10.0 (p = 0.001) compared with their controls, using the dichotomized variables." (PMID 38667723, 2024).
retinal degeneration (1 paper, 2024). Degeneration of the retina. "As FGF21 has therapeutic effects on retinal glial remodeling to preserve retinal function in retinal degeneration, pemafibrate-induced circulating FGF21 might contribute to glial modulation in carotid artery occlusion-induced ischemic retinopathy." (PMID 38791541, 2024).
retinitis pigmentosa (1 paper, 2021). Retinitis pigmentosa (RP) is an inherited retinal dystrophy leading to progressive loss of the photoreceptors and retinal pigment epithelium and resulting in blindness usually after several decades. "We recently reported that FGF21 preserved photoreceptor function via modulating Müller glial cells in P23H mice which mimic human retinitis pigmentosa." (PMID 34502311, 2021).
rheumatic diseases (1 paper, 2019). "Association between FGF21 and rheumatic diseases would be of interest as FGF21 ameliorates CIA by regulating oxidative stress and inflammatory response." (PMID 31443349, 2019).
thalassemia (1 paper, 2021). An inherited blood disorder characterized by a decreased synthesis of one of the polypeptide chains that form hemoglobin. "Plasma FGF21 level was separately related to cognitive dysfunction in thalassemia patients." (PMID 33850218, 2021). "Therefore, the conditions or medications that reduce plasma FGF21 levels, may help to improve cognitive function in thalassemia patients." (PMID 33850218, 2021). "These suggest that FGF21 may play a role in MCI in thalassemia patients." (PMID 33850218, 2021). "In addition, we postulated that there may be resistance to FGF21 in thalassemia patients." (PMID 33850218, 2021).
thyrotoxicosis (1 paper, 2022). A hypermetabolic syndrome caused by the elevation of thyroid hormone levels in the serum. "In two other studies, FGF21 was higher in patients with thyrotoxicosis than in healthy euthyroid controls and fell with treatment." (PMID 35929907, 2022). "As both FGF21 and leptin are elevated in thyrotoxicosis and as both are known to enhance energy expenditure, they may play an additive or synergistic role in promoting heat production in this condition." (PMID 35929907, 2022). "FGF21, which promotes thermogenesis, has been reported to be elevated in thyrotoxicosis." (PMID 35929907, 2022). "High levels of thermogenic hormones, leptin, and FGF21 were observed in thyrotoxicosis and may be partly responsible for the excessive heat production typical of this condition." (PMID 35929907, 2022). "Thus, thyrotoxicosis is a useful model for understanding the role of the thyroid hormones in regulating weight, energy production, and appetite, either directly or through various mediators like leptin, ghrelin, and fibroblast growth factor 21 (FGF21)." (PMID 35929907, 2022).
Tinnitus (1 paper, 2023). Tinnitus is an auditory perception that can be described as the experience of sound, in the ear or in the head, in the absence of external acoustic stimulation. "The top five proteins associated with tinnitus with a p value less than 0.02 were FGF-21, MCP4, GDNF, CXCL9, and MCP-1." (PMID 38079022, 2023).
tyrosine hydroxylase deficiency (1 paper, 2017). Tyrosine hydroxylase (TH) deficiency is an autosomal recessive disorder characterized by a spectrum of phenotypic features, based on severity and response to levodopa. "However, in the case of a child with tyrosine hydroxylase deficiency in whom FGF-21 was >5700 ng/L, a repeat measurement a year later showed FGF-21 to be 70 ng/L." (PMID 28825656, 2017).
ulcer (1 paper, 2023). "However, injection of the FGF21 recombinant protein was followed by subsiding duodenal intestinal wall edema, significantly relieved ulcer, and the epithelium was significantly improved and tended to be complete." (PMID 36968461, 2023).